S100A4 (S100 calcium binding protein A4)
Diseases named in the same sentence as S100A4 in open-access papers (continued):
Sharing a sentence is not in itself a finding about the gene and the disease.
tumor (continued). "Taken together, the present study demonstrated that CXCR5 triggered the differentiation of tumor cells into Schwann-like cells through repressing miR-187 to disinhibit S100A4, thus facilitating PNI of SACC." (PMID 34114971, 2021). "The SDC4-α5β1 integrin signaling through PKCα participates in TG2/S100A4-mediated tumor cell migration." (PMID 34282767, 2021). "Univariate analysis showed that exosomal S100A4 level, OPN level, tumor size, tumor capsule, and vascular invasion were significantly associated with OS and TTR of HCC patients." (PMID 34035222, 2021). "Because IL-4-activated macrophages cannot fully represent the characteristics of TME-educated TAMs, we further explored the in vivo roles of S100A4 in TAM alternative polarization toward a protumor phenotype using macrophages isolated from tumor grafts." (PMID 34145030, 2021). "While constitutively active Wnt signaling in the colon gives rise to adenocarcinoma, elevated levels of S100A4 in the primary tumor drives cancer progression up to the formation of distant metastases." (PMID 35008201, 2021). "As extracellular protein released by both tumor or stroma cells, S100A4 acts in either an autocrine or paracrine manner by binding to its cognate receptor RAGE, thereby triggering cell migration, invasion, and angiogenic responses." (PMID 33946884, 2021). "It was also reported that S100A4 levels were significantly increased in HCC samples compared with controls, moreover, S100A4 protein levels correlated with tumor differentiation, invasion, recurrence and overall survival." (PMID 33815482, 2021). "TAMs were isolated from the tumor grafts in whole-body S100A4-knockout (KO), macrophage-specific S100A4-KO and transgenic S100A4WT−EGFP mice (expressing enhanced green fluorescent protein (EGFP) under the control of the S100A4 promoter)." (PMID 34145030, 2021). "Afterwards, more evidence indicated S100A4 broadly participates in tumor progression and metastasis in varieties of cancers, especially in CRC." (PMID 33691630, 2021). "When siRNA against s100A4 was introduced into exosomes and administered to a mouse lung metastasis model, tumor growth was significantly inhibited." (PMID 34885247, 2021). "To validate the transcriptional cross-regulation of S100A4 and DKK1 in vivo, we analyzed the S100A4-regulated DKK1 expression in tumor tissue of xenograft mice after intrasplenic transplantation of HCT116 cells." (PMID 35008201, 2021). "The gene expression profile analysis demonstrated that the levels of S100A4/S100A6/S100A10/S100A11/S100A13/S100P were higher in tumor than in normal liver samples." (PMID 33815482, 2021). "Altogether, our results suggest that intracellular S100A4 promotes cell proliferation and EMT characteristics in tumor cells, and that secreted S100A4 activates osteoclastogenesis, contributing to osteolytic bone metastasis." (PMID 33549040, 2021). "Immunohistochemistry (IHC) staining of S100A4 in nude mice tumor models also confirmed that S100A4 was significantly more highly expressed in MHCC97-H derived tumors." (PMID 34035222, 2021). "S100A4 is another ligand of RAGE that has been shown to stimulate tumor proliferation and metastasis in various cancer types through its interaction with RAGE." (PMID 34360919, 2021). "To further compare detailed changes to the gene expression signature, we performed protein-coding mRNA-seq analysis of S100A4+ and S100A4− TAMs isolated from tumor grafts of E7710 tumor-bearing S100A4WT−EGFP reporter mice." (PMID 34145030, 2021). "Next, we further evaluated the roles of macrophage-specific S100A4 on TAM polarization using E7710 tumor-bearing mice of the paired S100A4M−WT and control S100A4M−KO strains." (PMID 34145030, 2021). "It is important to highlight the presence of S100A4 in the tumor stroma of HNSCCs, which is related to invasion and metastasis, where inflammatory cells can express S100A4 and contribute to the aggressive behavior of these tumors." (PMID 34204259, 2021).
tumor (continued). "Significantly inhibited tumor development was observed in the animals with macrophagic-specific S100A4 deletion compared with control animals." (PMID 34145030, 2021). "S100A4 can also be combined with other tumor biomarkers for early PC diagnosis and determination of PC prognosis, and the combinations can improve the accuracy of distinguishing PC from normal tissues to varying degrees." (PMID 34527585, 2021). "Synthetic NBD peptide blocked the interaction between S100A4 and MetAP2 in endothelial cells and inhibited tumor angiogenesis and prostate cancer growth in tumor-bearing mice." (PMID 34209679, 2021). "S100A4 was found as one of the most up-regulated genes in tumor samples, and its expression strongly correlated with patients aged less than three years at diagnosis of intracranial ependymoma." (PMID 33918416, 2021). "High DKK1 expression in the tumor tissue or microenvironment seems to compensate for the aggressive phenotype of elevated S100A4 expression in OS." (PMID 35008201, 2021). "Studies showed that S100A4 was highly expressed in metastatic tumor cells and the expression of S100A4 played a role in regulating GBM cell aggressiveness." (PMID 33004792, 2020). "Two other proteins known to play important roles in tumor progression exhibited 1400W-inhibitable upregulation in photostressed U87 cells: Survivin and S100A4." (PMID 33073206, 2020). "S100A4 is a promoting protein for epithelial–mesenchymal transition and plays an important role in facilitating tumor invasion and metastasis." (PMID 32696952, 2020). "As we demonstrated that S100A4 represented a crucial biomarker of tumor invasiveness and host organ colonization by M5-T1 cells, we next investigated the changes observed within S100 protein abundances in liver samples from G1, G2, and G3." (PMID 33207594, 2020). "This was essential to uncovering the association betweenS100A4 transcript abundance and the proportionof S100A4-positive tumour area." (PMID 32296879, 2020). "Among the list of markers of tumorigenesis/invasiveness that were previously identified, eight proteins evolved in a similar way in the spleens of tumor-bearing rats as in control rats, of which S100A4 was the most effected." (PMID 32290283, 2020). "In this context, S100A4 was shown to be a promising biomarker, as it correlated with tumour progression, morphologic changes related to EMT, invasion, and metastasis." (PMID 32722137, 2020). "α-SMA+S100A4+ CAFs can activate tumor immune response by promoting CD8+ T cell activation through fusion with dendritic cells." (PMID 33292666, 2020). "S100A4 silencing inhibited mitochondrial complex I activity, reduced cellular ATP levels, and decreased invasive and metastasic properties as well as tumor growth in vivo, suggesting a link between mitochondrial function and S100A4." (PMID 32397535, 2020). "S100-A4 is involved in cell cycle control, angiogenesis, motility, and cell adhesion, and therefore, related to tumor progression and metastasis." (PMID 32587372, 2020). "S100A1, S100A4 and S100B protein expression are related to the increasing levels of tumor malignancy." (PMID 31968004, 2020). "A comparative SWATH-MS analysis of two paraffin-embedded human MM tumor pieces (sarcomatoid vs. epithelioid) revealed a significant increase in S100A4 abundance in both the tumor and its periphery, and concomitantly in three EMT markers." (PMID 32290283, 2020). "Results showed that tumour cell‐derived RANTES had a significant effect on the increased level of extracellular S100A4 in blood circulation." (PMID 32307910, 2020). "S100A4 and S100A9 show common molecular interactions, both being associated with inflammation and in vivo tumor progression, reducing overall survival for the patient." (PMID 32290283, 2020). "S100A4 in the microenvironment secreted by cancer cells interacts with stromal cells around tumor cells to promote tumor metastasis." (PMID 33273928, 2020).
tumor (continued). "The strength of therelationship between mRNA expression of the tumour marker S100A4 and itsproportion score of quantitative immunohistochemistry (qIHC) was introduced as anexperimental readout to fine-tune the normalization choice." (PMID 32296879, 2020). "Five of 14 included studies in the meta-analysis indicated that tumor differentiation was correlated with S100A4 expression." (PMID 32696952, 2020). "The results showed that miR-125b expression was higher and S100A4 was lower in the SKOV3-LV-miR-125b mimic tumor tissues compared with the SKOV3-LV-miR-NC tumor tissues." (PMID 32842846, 2020). "We found that the novelnormalizer, HNRNPL, produced a shift from no tohigh significance for the correlation between mRNA abundance and the qIHC score ofthe tumour marker S100A4 compared to normalization by RNA input mass." (PMID 32296879, 2020). "S100A4 can not only be found in cancer cells but is also highly expressed in stromal cells of the tumour microenvironment (TME), such as fibroblasts, T-cells, macrophages, and neutrophils." (PMID 32722137, 2020). "It is widely accepted that there is a close relationship between S100A4 and non‐tumour pathophysiology, especially organ fibrosis." (PMID 32307910, 2020). "Increasing evidence showed that S100A4 in extracellular space is closely related to the progression of tumour metastasis 26, 27 and other human inflammatory diseases." (PMID 32307910, 2020). "We found that S100A4, along with 12 other biomarkers, differentiated neoplastic from preneoplastic mesothelial cell lines, and invasive vs. non-invasive tumor cells in vitro, and MM tumors in vivo." (PMID 32290283, 2020). "For this purpose, a number of proteins were selected, of which S100A4, an important member of the S100 protein family, actively participates in tumor progression and metastasis in various malignant tumors." (PMID 32290283, 2020). "Expression of miR-125b and S100A4 was analyzed using qRT-PCR and western blotting in tumor tissues, respectively." (PMID 32842846, 2020). "Surprisingly, studies have found that cytokine‐mediated pathways play an important role in stimulating S100A4 secretion in different types of normal cells and tumour cells." (PMID 32307910, 2020). "61, 83 and 83% of tumours showed moderate to strong staining for S100A4, S100A6 and S100A14, respectively, whereas only 22% were positive for S100A2." (PMID 31123345, 2019). "The results showed that BITC suppressed invasiveness and induced apoptosis in vitro, inhibited hematogenous metastases and tumor growth in vivo by blocking S100A4, and induced PUMA signal in OSCC." (PMID 30970087, 2019). "The expression patterns of S100A4 were also evaluated by qRT-PCR in Doc-sensitive (n=6) vs Doc-resistant (n=6) tumor samples from clinical PCa patients as well as the cells of DU145, DU145R, PC3 and PC3R." (PMID 31895690, 2019). "For example, S100A4, an important member of S100 family proteins, functions to increase tumor progression and metastasis through TGFβ/Smad, NFkB, and Wnt/β-catenin signaling pathways." (PMID 31608231, 2019). "CRISPR/CAS9-mediated knockout of S100a4 in a metastatic tumor-derived cell line disrupted its metastatic potential indicating a role for S100a4 in metastasis." (PMID 31881983, 2019). "As the histological analysis of femurs from mice that received intracardiac injection of mtMDA-S100A4sh revealed hardly any tumor mass in bones, we next sought to more directly assess the in vivo effect of S100A4 from mtMDA cells on osteoclasts." (PMID 31667000, 2019). "Together suggest S100A4 re-activate GemOE cells to secrete CCL2 that attracts macrophages and polarizes them into Gas6-secreting M2-tumor-associated macrophages (M2-TAMs42, 47, 48)." (PMID 31844158, 2019). "An increasing number of studies have revealed that S100A4 performs functions related to tumor growth and metastasis, and S100A4 is also overexpressed in many tumor tissues." (PMID 31526392, 2019).
tumor (continued). "Accordingly, inhibition of S100A4 expression in tumor cells suppresses their metastatic potential, representing, therefore, a strategy to counteract metastatic cancers." (PMID 31623154, 2019). "S100A4 participates in a variety of biological functions, including inhibition of tumor cell apoptosis, promotion of cell proliferation and angiogenesis, and cell motility." (PMID 31526392, 2019). "The increased expression of S100A4 correlated positively with PCa progression, which was consistent with observations in other tumor types, and with poorer OS among patients." (PMID 31895690, 2019). "Expression of S100A4 in different tumor cells has been shown to strongly correlate with aggressive metastatic tumor phenotype." (PMID 30446693, 2018). "The studies in the literature noted significant associations of the higher levels of S100A4 expression with the tumor localization, lymph node metastasis, TNM stages, and the depth of tumor invasion in patients with CRC." (PMID 30111999, 2018). "Thus, MDA-hyb1 presented higher in vitro proliferation as compared to MDA-hyb2 and accordingly, a faster tumor growth in vivo associated with a larger network of distant organ metastases which may be related in part to elevated S100A4 and more MDA-MB-231-like properties in MDA-hyb1." (PMID 29329589, 2018). "The distribution of the S100A4 staining in the tumor tissue was assessed in order to understand the patterns of the superficial, deep, and complete staining." (PMID 30111999, 2018). "It is suggested that MMP is stimulated transcriptionally by the S100A4 protein, contributing to the angiogenesis and invasion of the tumor cells." (PMID 30111999, 2018). "Our preclinical studies supported the strong potential of niclosamide as anti-cancer drug, which interferes with tumor progression and metastases formation via S100A4 inhibition." (PMID 29544454, 2018). "In contrast, MDSCs from S100A4−/− tumor-bearing mice showed a diminished resistance to the induction of intrinsic apoptosis." (PMID 29556233, 2018). "S100A4, an important member of the S100 protein family, serves to promote tumor progression and metastasis." (PMID 30111999, 2018). "Given that tumor metastasis is closely associated with EMT, we performed IHC staining for S100A4, a marker of EMT, in liver tissue samples." (PMID 29510695, 2018). "As the stage of the tumor advanced, the distribution of complete staining for S100A4 protein increased." (PMID 30111999, 2018). "The cell proliferation curve was increased by S100A4 overexpression, while was decreased by S100A4 suppression., Tumor volume was increased by S100A4 overexpression, while was decreased by S100A4 suppression (respectively)." (PMID 30045697, 2018). "The ability of S100A4‐activated basal‐like BCCs to promote tumor‐supportive phenotype in macrophages has been verified by functional characterization of CM‐S100A4‐educated THP1, denoted TAM‐like THP1." (PMID 29741811, 2018). "Seventeen days after tumor-cell inoculation, tumors in S100A4−/− mice were significantly smaller than tumors in WT control mice." (PMID 29556233, 2018). "We observed an inverse correlation between S100A4 transcript levels and the percentage of tumor cells." (PMID 29741811, 2018). "Several studies are available in the literature on the effects of S100A4 on tumor growth and metastases." (PMID 30111999, 2018). "On day 14, WT mice had a mean tumor volume of 957.26 mm3 compared with 602.84 mm3 for the S100A4−/− mice." (PMID 29449540, 2018). "In particular, the S100A4 protein is known to be secreted by tumor and/or stromal cells to support tumorigenesis by stimulating angiogenesis and promoting endothelial cell migration." (PMID 30060564, 2018). "Cytoplasmic expression of S100A4 protein was demonstrated in the tumor tissue of 132 patients (89.2%) out of a total of 148 study patients." (PMID 30111999, 2018).
tumor (continued). "We studied immune-cell types at the time point at which differences in tumor sizes between WT and S100A4−/− mice first became apparent." (PMID 29556233, 2018). "At day 21, tumor volumes in WT mice were approximately twofold greater than those in S100A4−/− mice." (PMID 29556233, 2018). "S100A4 is expressed not only in tumor cells, but also in various stromal cells, and secreted into the extracellular space." (PMID 29741811, 2018). "We have shown that the prometastatic microenvironmental factor S100A4 stimulates basal‐like BCCs to secrete factors/cytokines that convert monocytes into TAM‐like cells demonstrating tumor‐supporting functions." (PMID 29741811, 2018). "The results provide direct evidence of cross talk between S100A4, autophagy and tumor growth and reveal a novel mechanism for lung tumor development." (PMID 29449540, 2018). "The secretion of S100A4 by tumor and stromal cells is believed to serve as a key player in promoting the metastasis of cancer cells or affecting angiogenesis." (PMID 29449540, 2018). "We concluded that increased MDSC apoptosis resulted in the impaired accumulation of MDSCs in tumor-bearing S100A4−/−mice." (PMID 29556233, 2018). "The protein expression levels of S100A4 in tumor tissue were matched with the clinicopathologic factors including patient survival." (PMID 30111999, 2018). "In this study of ours, it was noted that the S100A4 protein was a factor increasing the aggressiveness of the tumor and the occurrence of lymph node metastases." (PMID 30111999, 2018). "In our model, fibroblasts were characterized by a significant decrease in S100a4 and a significant increase in Cd44 expression following co-culture with tumor cells in 3D." (PMID 29435153, 2018). "MDSCs isolated from the spleens of tumor-bearing WT mice (positive for S100A4) responded to the TLR4 inhibitor with significantly increased apoptosis compared with that in control MDSCs." (PMID 29556233, 2018). "In conclusion, we have shown that extracellular S100A4 instigates a tumor‐supportive microenvironment, involving a network of cytokines and TAM‐like cells, which was particularly characteristic for basal‐like BCCs and potentiated their aggressive properties." (PMID 29741811, 2018). "CD133+ patients had higher levels of S100A4 in tumor cells than CD133− patients (2.10 ± 0.21 vs. 1.12 ± 0.20, p = 0.001)." (PMID 29510695, 2018). "S100A4 protein level is upregulated in tumor cells, and its suppression by a neutralizing antibody is shown to reduce tumorigenesis and angiogenesis." (PMID 29507695, 2018). "At the end of the experiment, the tumor volumes were 1607.93 mm3 for the WT group and 984.71 mm3 for the S100A4−/− group." (PMID 29449540, 2018). "Using TLR4 knockout (TLR4−/−) mice with the MCA205 tumor model confirmed the involvement of TLR4 in S100A4-dependent signaling in vivo." (PMID 29556233, 2018). "On the other hand, the facilitation of the S100A4 expression along with the advanced stages of the tumor is the most significant finding as the tumor staging is the most important factor in terms of the prognostic value." (PMID 30111999, 2018). "The S100A4 protein expressed intracellularly moves to the extracellular space leading to the migration, invasion, and metastasis of the tumor cells." (PMID 30111999, 2018). "The effect of S100A4‐activated BCCs on macrophage differentiation, M2 polarization, and production of tumor‐promoting cytokines suggests the formation of protumorigenic TAM‐like cells." (PMID 29741811, 2018). "The majority of cells with inhibited β-catenin had significantly more LC3 puncta than those without inhibited β-catenin.These results suggest that S100A4 inhibited autophagy to promote tumor cell survival via the Wnt/β-catenin pathway." (PMID 29449540, 2018).